ALB (albumin)
Diseases named in the same sentence as ALB in open-access papers (continued):
Sharing a sentence is not in itself a finding about the gene and the disease.
anemia (continued). "Among females, waist circumference, albumin levels, being an NNRTI based regimen and microcytosis was also associated with anemia in this cohort but this relationship was abrogated by male sex as no variable remained statistically significant on multivariable analysis." (PMID 40063574, 2025). "Biological alterations such as anaemia, neutrophilia, platelet disorders, increased liver enzymes and decreased albumin/globulin (A/G) ratio may occur frequently, but haematological and biochemical changes after surgery have yet to be reported." (PMID 39814065, 2025). "The mild anemia and slightly lowered albumin levels noted in the patient’s preoperative tests might have indicated a compromised immune system, making them more vulnerable to opportunistic infections like MAC." (PMID 40313643, 2025). "Therefore, age and normal albumin levels were protective factors, and the inability to self-care preoperatively, a low PLT count, and anemia were risk factors for the inability to self-care postoperatively." (PMID 38606152, 2024). "Furthermore, proximal gastrectomy confers several advantages in terms of weight maintenance, postoperative anemia and nutrition (including vitamin B12, protein, albumin and cholesterol)." (PMID 39497709, 2024). "In symptomatic patients aged 30 to 39, the PPVs for cancer associated with blood test abnormalities were lower; the only symptom/result combinations with PPVs >3% were for males with abdominal pain and either anaemia, low albumin, or low ferritin and females with either symptom and raised CA125." (PMID 39078806, 2024). "Our study revealed a significant negative association between albumin levels and anemia development following chemotherapy in osteosarcoma patients, consistent across all models." (PMID 39621534, 2024). "The study observes the effects of vitamin C in combination with albumin-bound paclitaxel and gemcitabine compared to chemotherapy alone on anemia, hand/foot numbness, pain, and quality of life in patients with advanced pancreatic adenocarcinoma with distant metastases." (PMID 39075587, 2024). "Moreover, laboratory findings indicated the possibility of MM, as evidenced by anemia, the reversed albumin-globulin ratio, and rouleaux formation observed on peripheral blood smear analysis." (PMID 39058808, 2024). "Women also tended to be more prone to anemia, with higher total protein and albumin levels." (PMID 39796450, 2024). "Therefore, it is worth considering testing for albumin and total protein levels in patients with CD, with a particular indication in patients with CD with anemia." (PMID 38337459, 2024). "His liver dysfunction soon progressed to ALF as elevation of transaminases (AST 870 U/l, ALT 263 U/l) with reduction of protein synthesis (PT-INR 1.53) and hypoalbumininema (albumin 2.47 g/dl), remarkable anemia (hemoglobin 6.3 g/dl), and thrombocytopenia (platelet count 19,000/μl)." (PMID 38807157, 2024). "Chronic inflammation is associated with the release of acute-phase proteins, which may negatively correlate with low albumin levels and, consequently, the development of anemia." (PMID 39797126, 2024). "Also, the increasing GDF-15 level was determined by a decreasing hepcidin level as well as the presence of anemia and renal dysfunction, and the decreasing hepcidin level was determined by decreasing stored iron and decreasing albumin levels." (PMID 38883134, 2024). "As modifiable preoperative risk factors, patients may benefit from preoperative interventions to correct anemia and lower albumin level to avoid unnecessary blood transfusion." (PMID 38840126, 2024). "Patients presenting with diarrhea should undergo a comprehensive set of laboratory tests to investigate the possibility of concurrent conditions, such as celiac disease, anemia, electrolyte abnormalities, low albumin levels, or treatment-related thyroid toxicities." (PMID 39311981, 2024).
anemia (continued). "In addition, leukocytosis, mild anemia, and low serum albumin levels observed before treatment were significantly improved, and no adverse events occurred throughout the treatment period." (PMID 38835791, 2024). "Predictive factors included anemia, low albumin levels, and elevated D-dimer." (PMID 39188469, 2024). "Therefore, ESR is relatively insensitive to the inflammatory process, especially for patients with systemic rheumatic diseases and those with concomitant renal insufficiency, low albumin, and anemia." (PMID 39768820, 2024). "This can be reflected by anemia, low albumin, and elevated CRP." (PMID 37878974, 2023). "It is interesting what happens in relation to the subdivision by ISS; in fact, as the stage progressed, we observed a reduction in albumin, an increase in the values of the total plasma proteins, and a significant decrease in the albumin/fibrinogen ratio, but, above all, a worsening of anemia." (PMID 36979941, 2023). "A history of severe prematurity, anemia, lymphopenia, elevated PCT and LDH and low levels of albumin and HDL cholesterol are associated with an increased risk of severe pneumonia; therefore, the presence of these data should put us on alert in the care of these patients." (PMID 37892366, 2023). "The first tests on admission revealed that patients with decreased lymphocyte counts and percentages, anemia, coagulation disorders, abnormally elevated myocardial zymogram indices, and decreased albumin and calcium levels might have more severe disease." (PMID 36817453, 2023). "Notably, age, female and BMI were positively correlated with anemia, whereas total cholesterol, eGFR, albumin, serum iron, white blood cells and SUA were negatively associated with anemia." (PMID 37291524, 2023). "Furthermore, they showed obvious signs of cachexia, such as anemia, inflammation, and low serum albumin." (PMID 37893197, 2023). "A complete blood count, electrolytes, and albumin should be obtained since patients with microscopic colitis may have mild anemia and, in rare cases, a protein-losing enteropathy." (PMID 37445477, 2023). "Compared to the patients with a high GNRI, the patients with a low GNRI were older, had a higher prevalence of anemia, acute subdural hematoma, and subarachnoid hemorrhage, had a higher age-adjusted Charlson Comorbidity Index value, and had lower levels of albumin, lymphocytes, and hemoglobin." (PMID 37082444, 2023). "In particular, high RDW value remains associated with vertebral fractures even after adjusting for all considered possible confounders: age, BMI, menopause, nutritional status (total protein, albumin, calcium phosphate), smoking, osteoporosis and anemia (OR = 4.1, 95% CI 1.67–11.4, p = 0.003)." (PMID 37061647, 2023). "In this report, we explored the association between LRG1 and anemia in school-aged children by assessing the correlation between LRG1 and several iron deficiency markers, including Hb, iron, percentage of transferrin saturation, albumin, and RDW." (PMID 37513518, 2023). "It should be emphasized that leukopenia, lymphopenia, neutropenia, trombocytopenia, anemia (both women and men), decreased concentrations of ferritin, total protein, albumin, vitamin D, vitamin B12 and folic acid were most common in patients with normal weight." (PMID 37762958, 2023). "Furthermore, patients with anemia showed significantly lower serum calcium, albumin and 1,25(OH)2D3 concentrations and higher serum P, iPTH and iFGF23." (PMID 36432528, 2022). "In addition, severe progressive anemia (n = 10, 71%) and low plasma albumin levels (n = 8, 57%) were observed during the disease course, probably due to bleeding and malabsorption in the GI tract; four patients ultimately required blood transfusions." (PMID 36288164, 2022). "Anemia or low serum albumin are also common complications of CKD." (PMID 36292142, 2022).
anemia (continued). "Compared with a baseline before dialysis, anemia, low albumin, blood pressure, blood urea nitrogen, creatinine, uric acid, potassium, calcium, phosphorus, and parathyroid hormone improved after 6 and 12 months, while the residual renal function gradually decreased during the follow-up." (PMID 35180850, 2022). "Furthermore, anemia and nutritional status were adequately controlled as indicated by 11.6 ± 1.4 g/dL of hemoglobin level and 39.4 ± 5.7 g/L of serum albumin as well as electrolyte disorders." (PMID 35456216, 2022). "Additional exams showed hypercholesterolemia, severe anemia, and normal serum albumin." (PMID 36275808, 2022). "Laboratory work up was significant for leukocytosis (26,000/mm3) with neutrophil predominance, microcytic anemia, low albumin, prolonged prothrombin time and International Normalized Ratio (INR), and elevated inflammatory markers including CRP, procalcitonin, ferritin and D-dimer." (PMID 36683795, 2022). "Blood tests showed mild anemia with 10.3 g/dL Hb and low albumin levels at 2.5 g/dL." (PMID 35928693, 2022). "In patients stratified by the sarcopenia index, variables including age, gender, smoking, alcohol, BMI, NRI, anemia, albumin, VATI, TATI, primary tumor locations, tumor length, treatment strategies, TNM stage, T stage, and N stage were similar between the two subgroups." (PMID 35501704, 2022). "The subgroup analysis categorized based on eGFR < 60 ml/min/1.73 m2, proteinuria > 1 g/d, albumin < 30 g/l, anemia, uric acid, and TG suggested that patients both presenting with AS and eGFR < 60 ml/min/1.73 m2 had a significant trend for a shorter time to reach end point than other subgroups." (PMID 34869465, 2021). "There were significant differences in CLR according to age (p=0.003), sex (p<0.001), smoking history (p<0.001), BMI (p=0.020), histology (p<0.001), tumor size (p<0.001), TNM stage (p=0.006), serum albumin level (p=0.001), and anemia (p<0.001) when Mann-Whitney U test was applied." (PMID 34149913, 2021). "In addition to abnormal cardiac markers, patients with MACEs also have anemia, decreased albumin, and coagulation disorders." (PMID 34722671, 2021). "Univariable Cox hazards analyses showed that subjects with male sex, Raynaud’s phenomenon onset after the age of 45, disease onset after the age of 50, cardiac involvement, PAPs > 35 mm Hg, DLCO <70%, FVC <65%, SRC, anemia, CRP > 5 mg/l, and albumin < 35 g/l had a higher risk of death." (PMID 34876194, 2021). "Albumin levels (<33 g/L) were protective from anemia (p = 0.02)." (PMID 33467587, 2021). "The presence of anaemia or electrolyte disorders should be corrected before surgery, and for those infants who are not able to accept oral liquid nourishment after surgery, total venous nutrition and albumin should be used to provide positive nitrogen balance." (PMID 34121552, 2021). "Blood analysis showed neutrophilia and eosinophilia in infected goats, in addition to anemia; significant decreases in total protein, globulin, albumin, and glucose levels; and significant increases in aspartate transaminase and alanine aminotransferase levels." (PMID 34475695, 2021). "Lower serum albumin and anemia may lead to prerenal hypoperfusion and renal ischemic-hypoxic injury, which aggravate the renal function." (PMID 34606471, 2021). "Anaemia, low albumin and elevated d-dimer were independent predictors of CVST in patients with IBD." (PMID 34417546, 2021). "Significant differences were found among the 4 groups in age, sex, Charlson comorbidity score, current smoker status, primary tumor location, type of gastrectomy, pathological TNM stage, tumor stage, lymph node stage, number of lymph nodes dissected, preoperative serum albumin, and anemia." (PMID 33628601, 2021). "Anaemia, low albumin and elevated d-dimer levels were predictive factors for CVST in our study." (PMID 34417546, 2021). "Anaemia, low levels of albumin and elevated d-dimer were predictive factors." (PMID 34417546, 2021).
anemia (continued). "In addition, participants in the first quintile of serum albumin level had a significantly higher rate of anemia and renal insufficiency compared with those in the fifth quintile of serum albumin level." (PMID 34055818, 2021). "Moreover, in this study, the extent of anemia among CKD patients which is an important nutritional status indicator was determined by using the serum value of albumin." (PMID 34237068, 2021). "Several studies showed that patients with advanced gastric cancer were more prone to anemia and reduced nutritional status than patients with early gastric cancer, and low levels of hemoglobin and serum albumin also indicated a poor prognosis for patients with gastric cancer." (PMID 33997045, 2021). "Hepatocytes respond to IL-6 by diminishing albumin production and producing several acute phase proteins and hepcidin, which in turn leads to reduced intestinal iron absorption, impaired release of iron stored in the macrophages, and anemia." (PMID 33777463, 2021). "All the patients had a degree of anemia before surgery, which worsened shortly after surgery despite minimizing intra-operative fluids, use of albumin, and using pediatric tube phlebotomy [Median ΔHb (pre-Hb-post-Hb): 1.13 mg/dL; Median ΔHct (pre-Hct-post-Hct): 2.3%]." (PMID 33392250, 2020). "Additionally, the CCI, preoperative albumin, preoperative anemia, surgical technique, the use of intraoperative vasoactive medication, and the volume of intraoperative fluid administration were associated with postoperative complications." (PMID 33085700, 2020). "The criteria included weight loss ≥5% in 12 months or low BMI (<20 kg/m2) with 3 of 5 of the following features: decrease muscle strength, fatigue, anorexia, low fat-free mass index, of abnormal biochemistry (increased inflammatory markers, anaemia and low serum albumin)." (PMID 32047177, 2020). "Higher levels of RDW were independently related to anemia, B-symptoms, and low albumin." (PMID 33158258, 2020). "Our findings reveal that hyperglycemia was associated with a systemic pro-inflammatory state characterized by elevation of WBC counts and increased levels of liver transaminases, total cholesterol and triglycerides in serum, whereas albumin and hemoglobin levels were decreased, suggesting anemia." (PMID 32059707, 2020). "Therefore, concluding that GA is superior to HbA1c as a mortality marker in these patients is premature, although some data suggest that GA is less affected by anemia and serum albumin levels than HbA1c is." (PMID 30824808, 2019). "• Loss of lean tissue mass, with a weight loss >5% of body weight in 12 months; Or• BMI lower than 20, plus three of the following: decreased muscle strength, fatigue, anorexia, low fat-free mass index, increase of inflammation markers such as CRP or IL-6, anemia, and low serum albumin." (PMID 31681777, 2019). "In addition, Killip class > 1, anaemia, albumin, uric acid, number of stents and LVEF were independent predictors of MACCEs in STEMI patients within 1 year after PCI." (PMID 31722708, 2019). "After adjusting for age and other potential confounding factors, multivariate logistic regression showed that the TyG index, Killip class > 1, anaemia, albumin, uric acid, number of stents and LVEF were independent predictors of MACCEs in STEMI patients after PCI (all P < 0.05)." (PMID 31722708, 2019). "However, a large paediatric controlled trial of fluid resuscitation (FEAST trial) examining boluses of 20–40mls/kg of 0.9% saline and 5% human albumin in African children with shock, including 987 (32%) with severe anaemia (Hb <5g/ld)." (PMID 31633055, 2019). "The patient in case 2 had fever for 10 days; only 2 principal clinical features (rash and cervical lymphadenopathy); but 5 laboratory findings (significantly elevated WBC count, anemia, platelet count of >450,000 after the 2 weeks of fever, albumin <3.0 g/dL, and an elevated ALT level)." (PMID 31770238, 2019).
anemia (continued). "On univariate analysis, factors associated with worse PFS included ECOG performance status ≥2 (vs. ≤1: p=0.041), Ann Arbor clinical stage (CS) ≥3 (vs. ≤2: p<0.001), G≥2 anemia (vs. G≤1: p=0.001), serum albumin <3.5 g/dL (vs. ≥3.5 g/dL: p=0.008), and BM involvement (vs. negative: p<0.001)." (PMID 29589833, 2018). "Patients who withdrew very early in our study were older in age, displayed markers of poor nutritional status (lower albumin levels and lower serum creatinine levels) and displayed several symptoms of severe uremic syndrome (e.g., anemia, hypocalcemia and decreased volume of 24 h urine output)." (PMID 29297246, 2018). "The patient’s laboratory results were low blood albumin and globulin, anemia, and leukopenia." (PMID 29734941, 2018). "In addition, previous reports have indicated that poor nutritional status, reflected by low serum albumin and anemia, can be clinical predictors of early mortality from TB." (PMID 30423855, 2018). "The most common abnormalities were high levels of LMR (512/707,72.4%), lymphocyte (334/707, 47.2%), monocyte (321/707, 45.4%), ALT (268/707, 37.9%), neutrophil (248/707, 35.1%), LDH (192/707, 27.2%), platelet (160/707, 22.6%), low albumin level (105/707, 14.9%) and anemia (64/707, 9.1%)." (PMID 28055965, 2017). "Previous studies have reported that old age, preoperative anemia, high uric acid levels, low serum albumin levels, furosemide medication, long surgery and CPB time, intraoperative inotropes use and large volume transfusion were associated with postoperative AKI." (PMID 28472145, 2017). "Laboratory examination may demonstrate a normal or abnormal aspect, such as an elevation of the Erythrocyte Sedimentation Rate (ESR), thrombocytosis, mild anemia, or an elevation of serum albumin or alkaline phosphatase." (PMID 28103792, 2017). "Serum leptin was related to anemia, albumin, and bone metabolism disorders in CKD patients." (PMID 27307101, 2016). "The serum biochemical profiles of these patients indicated that they had fair nutrition status (albumin, 3.9 ± 0.4 g/dL; total cholesterol, 160 ± 45 mg/dL), mild anemia (hemoglobin 10.2 ± 3.6 mg/dL), fair dialytic clearance, and nearly normal electrolyte panels." (PMID 26998414, 2016). "The loss of residual urine volume, financing not secured of HD, hypervolemia, not taking ACE inhibitor and betablocker, central line catheter as a vascular access normal serum albumin levels and anemia have emerged as the main independent predictors of all-cause mortality in this study." (PMID 27871253, 2016). "Anemia, reduced albumin, and reduced platelets were all unfavorable for OS." (PMID 27703488, 2016). "In pregnancy fructosamine falls because of changing albumin dynamics and dilution anemia and these factors may contribute to differences across our study groups." (PMID 27736899, 2016). "Therefore, the extent of contribution of low serum albumin alone in the development of anemia or hyporesposiveness to ESA requires further prospective study." (PMID 26644884, 2015). "Cachexia is defined as weight loss of 5% in the previous 12 months accompanied by decreased muscle strength, fatigue loss of appetite, low fat-free mass index or abnormal biochemistry (including increased inflammatory markers, anaemia (<120 g/l) or low serum albumin (<32 g/l))." (PMID 25710625, 2015). "The findings of this longitudinal study showed that hemodialysis patients with lower concentration of baseline serum albumin had significantly higher prevalence of anemia at the end of the study period indicating lower rate of response to conventional therapy of anemia." (PMID 26644884, 2015). "Conversely, a recent pilot study conducted in 15 CKD patients on hemodialysis treatment for at least 6 months has shown that 3 month EAAm supplementation increased serum albumin and total proteins, with reduced levels of inflammatory markers and improved anemia." (PMID 24923264, 2014).